TREM2 (triggering receptor expressed on myeloid cells 2)
Diseases named in the same sentence as TREM2 in open-access papers (continued):
Sharing a sentence is not in itself a finding about the gene and the disease.
ischemic stroke (continued). "Alteration of TREM2 expression levels in vitro and in vivo regulates the production of pro‐ and antiinflammatory mediators as well as the conversion of microglial phenotypes after ischemic stroke." (PMID 32757264, 2020). "Moreover, we demonstrated that DHA treatment enhanced MANF, decreased TREM2 expression, reduced ischemic brain injury, activated neurogenesis, and promoted functional recovery after experimental ischemic stroke." (PMID 32757264, 2020). "However, it should be noted that the temporal dynamics of TREM2 expression and effector mechanisms in ischemic stroke remain to be elucidated and current insights in TREM2 function are mainly derived from different disease models and cell types." (PMID 31379859, 2019). "However, the role of the TREM2-TLR interaction in ischemic stroke remains to studied into more detail." (PMID 31379859, 2019). "Targeting TREM2 to inhibit the inflammatory response in ischemic stroke may be a new therapeutic option." (PMID 31031649, 2019). "While ongoing research is focusing on the link in AD between TREM2 mutants and the APOEε4 isoform, which is the major risk factor for AD, the association of TREM2 and APOE in ischemic stroke and their putative intertwined signaling remains unclear." (PMID 31379859, 2019). "Although post-ischemic inflammation induced by the innate immune response is considered an essential step in the progression of cerebral ischemia injury, the role of triggering receptor expressed on myeloid cells 2 (TREM2) in the pathogenesis of ischemic stroke remains to be elucidated." (PMID 28592261, 2017). "To confirm the role of TREM2 during ischemic stroke in vivo, we used the TREM2 siRNA approach." (PMID 28592261, 2017). "Pharmacological targeting of TREM2 to suppress the inflammatory response may provide a new approach for developing therapeutic strategies in the treatment of ischemic stroke and other cerebrovascular diseases." (PMID 28592261, 2017). "Importantly, the beneficial neuroprotective and anti-inflammatory effects of EE were abolished when TREM2 was knocked down, underscoring the essential role of TREM2 in mediating the effects of EE on neuroinflammation and cognitive function after ischemic stroke and surgical trauma." (PMID 39758888, 2024). "Our findings indicated the importance of Trem2‐Igf1 axis in regulation of microglial activities, particularly those related with microglial glucose metabolism, and further shed light on the therapeutic potentials of targeting microglial immunometabolism in ischemic stroke." (PMID 38151703, 2024). "However, the role of TREM-2 in ischemic stroke remains uncertain." (PMID 39062850, 2024). "However, the mechanism of TREM2-promoted remyelination remains unclear, though TREM2 up-regulation after ischemic stroke is protective for neurological function." (PMID 36829205, 2023). "However, the precise role of TREM2 in ischemic stroke inflammatory response remains elusive." (PMID 28592261, 2017). "Furthermore, in the context of ischemic stroke, the expression of perilipin-2 (Plin2) is upregulated, and the expression of ATP-binding cassette transporter A1 (ABCA1) is downregulated, leading to increased lipid droplet formation and impaired cholesterol clearance in TREM2-deficient microglia." (PMID 40242752, 2025). "Altogether, our study indicates that supplementation of cyclocreatine targeting microglial metabolism may be promising for therapeutic intervention in ischemic stroke, even in the absence of Trem2, the mechanisms of which is closely associated with regulation of Igf1 expression." (PMID 38151703, 2024). "Ultimately, our findings suggest that TREM2 activation induced by EE mitigated neuroinflammation and POCD in ischemic stroke mice, an effect that was, at least in part, mediated by the activation of the PI3K/Akt signaling pathway." (PMID 39758888, 2024).
ischemic stroke (continued). "TREM-1 (Triggering Receptor Expressed on Myeloid Cells-1) and TREM-2 (Triggering Receptor Expressed on Myeloid Cells-2), as members of the TREM family, have been increasingly recognized for their roles in the inflammatory response and prognostic evaluation of ischemic stroke." (PMID 40869247, 2025). "For instance, triggering receptor expressed on myeloid cells 2 (TREM2) was mostly expressed in microglia, but not in neurons, astrocytes, or oligodendrocytes in ischemic stroke." (PMID 31031649, 2019). "In the present study, we hypothesized that activation of TREM2 by EE could improve neurological deficits and attenuate neuroinflammation triggered by surgical trauma via the PI3K/Akt signaling pathway in a mouse model of ischemic stroke." (PMID 39758888, 2024). "If the p.R47H mutation in TREM2 affects the same pathway, this could provide a possible explanation for our lack of association with ALS, PSP and ischemic stroke." (PMID 23800361, 2013). "In our study, we selected EE as a non-pharmacological TREM2 agonist, with the goal of mitigating POCD by exposing mice with ischemic stroke to enriched environmental stimuli during the perioperative period." (PMID 39758888, 2024).
glioma (33 papers, 2016 to 2025). A benign or malignant brain and spinal cord tumor that arises from glial cells (astrocytes, oligodendrocytes, ependymal cells). "Studies have shown that high expression of TREM2 is associated with poor prognosis in patients with gastric cancer, glioma, and renal cell carcinoma." (PMID 39838454, 2025). "TREM2 (triggering receptor expressed on myeloid cells 2), which is normally expressed on the brain’s immune cells, is associated with a poor prognosis in glioma if overexpressed in macrophages and microglia." (PMID 38534769, 2024). "In contrast, the study found that high TREM2 expression was associated with worse overall survival in lower grade glioma, liver hepatocellular carcinoma, and kidney renal clear cell carcinoma." (PMID 36119485, 2022). "Less than a handful of genes are well described to be active in AD (e.g., CASP3) but decrease in glioma; or upregulated in glioma and being a risk variant in AD leading to gene deficiency (e.g., TREM2)." (PMID 31824268, 2019). "On the other hand, a recent study reported that TREM2 is significantly upregulated in glioma tissue and is associated with glioma progression (Wang X.-Q." (PMID 31824268, 2019). "Wang and colleagues found that TREM2 deficient glioma cell lines downregulated CXCL10, CXCR3, MMP2 and MMP9 which are all important in tissue invasion." (PMID 28768545, 2017). "Here, considering the association between TREM2 and central nervous system disease, we sought to study the role of TREM2 in glioma development." (PMID 26506595, 2016). "TREM2-siRNA treatment caused a significant decrease in the adhesive capacity of both glioma cells (P < 0.001)." (PMID 26506595, 2016). "have revealed that TREM2 expression is significantly higher in mesenchymal gliomas compared to other subtypes, and its high expression is closely associated with poor prognosis in glioma patients." (PMID 40242752, 2025). "Originally a focus of research in neurodegenerative diseases like Alzheimer’s Disease with a potential beneficial role, triggering receptor expressed on myeloid cells 2 (Trem2) in glioma is believed to be widely expressed by disease-associated, inflammatory microglia." (PMID 39409905, 2024). "Moreover, myeloid TREM2 promotes MHCII-associated CD4+ T cell responses against gliomas." (PMID 39838454, 2025). "Apoe is associated with lipid delivery to tumor cells and lipid recycling by macrophages in necrotic areas, while Trem2 is a known phagocytic immunomodulator in gliomas and promotes microglial survival." (PMID 40674254, 2025). "With the emergence of monoclonal antibody targeting TREM2, this avenue of treatment seems promising for modulating the immune environment in glioma patients." (PMID 38515213, 2024). "Several studies have shown that the expression levels of TREM2 in glioma tissues are significantly increased, and it is an oncogene." (PMID 38725629, 2024). "Trem2 in human glioma cells and human microglia was upregulated following segregated coculture with each other compared to that following coculture with themselves." (PMID 38750472, 2024). "In the glioma study, silencing of TREM2 led to a decrease in cell adhesion as well as decreases in the migratory and invasive capacities of both cell lines." (PMID 36119485, 2022). "As TREM2 played a pivotal role in the glioma immune response, we analyzed its potential for predicting patient prognosis." (PMID 36713360, 2022). "In this research, the expression patterns of TREM2 in glioma were analyzed, along with its prognostic value and functional roles." (PMID 36713360, 2022). "To validate further the significance of TREM2 in glioma immune response, we first drew a heatmap to illustrate the correlation between TREM2 and several genes involved in immune function." (PMID 36713360, 2022). "Data on TREM2 expression in epithelial tumor cells is still limited, but two studies, one in renal cell carcinoma (RCC) and one in glioma have been conducted that point to an oncogenic role of TREM2." (PMID 36119485, 2022).
glioma (continued). "To investigate the molecular expression pattern of TREM2, we explored the distribution of TREM2 expression in different molecular subtypes of glioma, which were identified by the TCGA network based on transcriptomic and genomic dimensions." (PMID 36713360, 2022). "TREM2 is highly expressed in mesenchymal subtype glioma which is characterized by stronger immunosuppression." (PMID 36713360, 2022). "TREM2 expression is increased in glioblastomas, gliomas with a mesenchymal subtype, gliomas with wild-type isocitrate dehydrogenase, and gliomas without 1p/19q deletion, all of which suggest the aggressiveness and poor prognosis of gliomas." (PMID 36713360, 2022). "Meanwhile, TREM2 regulated the M2 phenotype polarization and augmented co-cultured glioma invasiveness." (PMID 36713360, 2022). "Through an in-depth analysis of the biological functions of TREM2 in glioma, we found that TREM2 played an important role in glioma-induced immune suppression." (PMID 36713360, 2022). "To explore biological processes related to TREM2 expression in glioma, we performed Pearson’s correlation analysis to screen genes strongly positively correlated with TREM2 (Pearson R> 0.5, p<0.0001)." (PMID 36713360, 2022). "A series of bioinformatic analysis methods, including gene ontology analysis, KEGG analysis, gene set variation analysis, and CIBERSORT, were employed to find out the role of TREM2 in the glioma immune process in our study." (PMID 36713360, 2022). "We found glioma cells that co-cultured with TREM2-knockdown THP-1 cells exhibited reduced invasive capacity compared with control group." (PMID 36713360, 2022). "To investigate the significance of TREM2 in glioma progression, we analyzed the RNA-seq data of bulk tumor tissues from patients with different molecular pathological backgrounds obtained from TCGA and CGGA databases." (PMID 36713360, 2022). "To further investigate the influence of TREM2 in glioma immune response, we analyzed the correlation between TREM2 and inflammatory response." (PMID 36713360, 2022). "TREM2 expression, WHO Grade, age at diagnosis, IDH status, and 1p/19q co-deletion status were found to be significantly associated with glioma patients’ overall survival." (PMID 36713360, 2022). "Immunosuppressive MDMs constitute a promising target for glioma treatment, whereas the enhancement of a microglia phagocytotic activity via Trem2 proved its efficacy in preclinical studies and is currently in a clinical phase 2 trial." (PMID 33809675, 2021). "The results demonstrated that, in 12 types of tumors, including breast cancer, colorectal cancer, lung cancer, glioma, and kidney cancer, TREM2 expression was related to TMB." (PMID 33679809, 2021). "Very interesting was the finding of a positive correlation of the level of HMGB1 in glioma patients with percentage of CD14+ TREM-2+ Mo (P = 0.007)." (PMID 32684831, 2020). "Further studies to elucidate the role of TREM2 in AD and glioma and its relation to microglia are needed." (PMID 31824268, 2019). "In glioma cell lines, liver cancer cell lines, and primary microglia, reduced levels of TREM2 led to cell cycle arrest." (PMID 28768545, 2017). "In culture, knocking down TREM2 reduced chemotaxis of glioma cells in a Boydon chamber assay in response to serum, and in the BV2 microglial cell line in a scratch assay." (PMID 28768545, 2017). "Compared with normal brain tissues, significant upregulation of TREM2 was observed in glioma tissues (P < 0.0001)." (PMID 26506595, 2016). "We then evaluated the apoptotic function of TREM2 in glioma cells by Annexin V-FITC/PI staining assay." (PMID 26506595, 2016). "To further explore its biological role in gliomas, we knockdown the expression of TREM2 in U87 and U373 cells, which expressed high levels of TREM2 by siRNA transfection." (PMID 26506595, 2016).
glioma (continued). "Flow cytometry analysis revealed that knockdown of TREM2 in both glioma cells significantly induced cell apoptosis approximately 12-fold compared with corresponding control cells (NC)." (PMID 26506595, 2016). "After 24 h of incubation, compared with the NC cells (104 ± 1 cells and 120 ± 1 cells), both TREM2-RNAi-U87 and TREM2-RNAi-U373 glioma cells showed significantly decreased migratory ability (46 ± 1 cells and 52 ± 1 cells, respectively, both P < 0.001)." (PMID 26506595, 2016). "In summary, our study demonstrated that the expression of TREM2 is significantly up-regulated in glioma tissues." (PMID 26506595, 2016). "We first tested the mRNA levels of TREM2 in 60 snap-frozen glioma tissues and 14 normal brain tissues using real-time quantitative PCR (RT-qPCR)." (PMID 26506595, 2016). "Depletion of TREM2 is able to suppress glioma cell growth and invasion by apoptosis, Cromer invasion and KEGG chemokine pathway." (PMID 26506595, 2016). "Our data provide new insights into the molecular function of TREM2 as well as its regulatory mechanisms in gliomas." (PMID 26506595, 2016). "Down-regulation of TREM2 in two glioma cell lines, U87 and U373, resulted in a significant reduction in cell proliferation, migration and invasion and a dramatic increase in S phase arrest and apoptosis." (PMID 26506595, 2016). "In the present study, we showed that up-regulation of TREM2 in human gliomas is closely related to tumor progression, and knockdown of TREM2 can inhibit the proliferation, adhesion, migration and invasion of glioma cells." (PMID 26506595, 2016). "Two TREM2 siRNAs (TREM2-siRNA-1 and TREM2-siRNA-2) were able to efficiently suppress endogenous TREM2 expression in both glioma cells, whereas TREM2 expression remained unaffected in control siRNA-transfected cells (NC)." (PMID 26506595, 2016). "According to the log-rank test and Kaplan-Meier analysis, the expression level of TREM2 in gliomas displayed a significant correlation with the patients' survival time (P < 0.05)." (PMID 26506595, 2016). "Microglia recruited by glioma are reported to acquire M2-like or mixed M1/M2-like phenotypes, thus the expression of anti-inflammatory markers CD163 and TREM2 by large proportions of PA-associated microglia supports the idea that these represent recruited microglia." (PMID 39948623, 2025). "However, the sphingolipids bind TREM2 on myeloid cells and elicit antitumor responses in central nervous system cancers." (PMID 41253786, 2025). "In this study, the prognostic value and functional roles of TREM2 in glioma were analyzed." (PMID 38370418, 2024). "However, in gliomas, TREM2 inhibits tumor progression by enhancing the phagocytosis of tumor cells and promoting MHC-II-related CD4+ T cell responses." (PMID 39135069, 2024). "Increased expression of TREM2 can promote cell proliferation, migration, and invasion, and it is strongly related to pathological grade and negatively related to overall survival of glioma patients." (PMID 38725629, 2024). "Trem2 in rGBM is an attractive marker given it may be highly expressed in an inflammatory glioma environment, possibly identifying microglia which has been driven to exhaustion." (PMID 39409905, 2024). "Trem2-knockdown THP-1 cells reduced the invasion ability of glioma cells when cocultured." (PMID 38750472, 2024). "It is suggested that TREM2+ monocytes play a protective role in gliomas." (PMID 38725629, 2024). "In glioma, overexpression of TREM2 enhances tumor cell proliferation and invasion." (PMID 36161280, 2023). "Furthermore, macrophage polarization experiment and co-culture system have shown that knocking down TREM2 decreased the M2 polarization, and inhibited the co-cultured glioma cells invasiveness." (PMID 36713360, 2022). "Next, we explore the expression of TREM2 in glioma tissues through IHC staining." (PMID 36713360, 2022).